SMARCA4 (SWI/SNF related BAF chromatin remodeling complex subunit ATPase 4)
Diseases named in the same sentence as SMARCA4 in open-access papers (continued):
Sharing a sentence is not in itself a finding about the gene and the disease.
cancer (continued). "However, resistance to EZH2 inhibitors are observed in ARID1A mutant cancers and recent data suggest that the switch of the SWI/SNF catalytic subunits from SMARCA4 to SMARCA2 underlies the acquired resistance to EZH2 inhibitors." (PMID 39471843, 2024). "Eleven of thirteen (85%) SMARCA4 mutation survival analyses in this review demonstrated significantly worse overall survival for SMARCA4-mutated NSCLC patients regardless of cancer treatment type." (PMID 39063938, 2024). "Notably, Proteolysis-targeting chimaeras (PROTACs)-induced knockdown of SMARCA4 exhibits pronounced anti-proliferative effects in AML cell lines, indicating that targeted degradation of BRG1 is a possible SMARCA4-dependent treatment strategy for cancer." (PMID 39187513, 2024). "Additionally, considering the functional roles of these co-occurred genes alongside SMARCA4’s function, further research is desired to unravel the comprehensive impact of these genetic interactions on cancer pathogenesis within the context of GEA." (PMID 38610978, 2024). "Moreover, analysis of genome-wide CRISPR screens for cancer genetic vulnerability (depmap.org) demonstrated the selective essentiality of SMARCA4 in NB cell lines, distinguishing it from most other cancers." (PMID 39174852, 2024). "Additionally, low SMARCA4 expression positively correlates with SMARCA2 CRISPR knockout effects when considering all cancer cell lines." (PMID 39174852, 2024). "Immunotherapy with ICIs has emerged as a promising treatment modality for SMARCA4-altered cancers." (PMID 39697230, 2024). "The potential role of SMARCA4 in different cancers was analyzed from available databases." (PMID 39125664, 2024). "The knockout of the SMARCA4 gene has been shown to induce apoptosis and kill cancer cells." (PMID 38446332, 2024). "Eight of 12 (75%) of cancers with protein-truncating SMARCA4 variants demonstrated a loss of SMARCA4 protein expression by IHC, whereas none of the seven cancers with pathogenic missense SMARCA4 variants demonstrated a loss of SMARCA4 protein expression." (PMID 38656564, 2024). "Recently, a subset of carcinomas originating in the sinonasal tract has been identified with distinct biological aggressiveness, characterized by the complete loss of SWI/SNF complex subunits, particularly SMARCB1 (INI1) and SMARCA4 (BRG1)/SAMRCA2." (PMID 39590317, 2024). "SMARCA4 knockdown robustly impaired cell proliferation and increased apoptosis of cancer cells." (PMID 36674511, 2023). "In hepatocellular carcinoma, SMARCA4 activates a series of downstream cascades by directly binding to the Sall4 promoter and enhancing Sall4 transcription, ultimately resulting in enhancing the stemness potency of cancer cells." (PMID 36674511, 2023). "(j) Using a model trained to predict SMARCA4 biallelic LOF in HMF cancers of unknown primary, we evaluate the predictive power across individual cohorts (one-tailed Wilcoxon rank-sum test), displaying significant cohorts separately (colours as in h)." (PMID 36883553, 2023). "Furthermore, mutations in SMARCB1 and SMARCA4 lead to widespread changes in the H3K27Me3 distribution, changing gene expression patterns, and suggesting that PRC2 can be targeted in these cancers." (PMID 37093326, 2023). "While SLC38A2 also mediates alanine uptake, alanine deprivation did not impact the growth of SMARCA4/2-deficient cancer cells, supporting the dominant contribution of glutamine in this context." (PMID 37210563, 2023). "On the contrary, SMARCA4 interacts with TGFB2-AS1 long non-coding RNA in breast cancer, resulting in transcriptional repression of TGFB2 and SOX2, and therefore, leading to attenuation of TGF-β signaling and loss of cancer stem cell-like characteristics." (PMID 36674511, 2023). "Therefore, the use of selective inhibitors in inhibiting SMARCA2 activity has become a new therapeutic strategy in SMARCA4-mutant cancers." (PMID 36770884, 2023).
cancer (continued). "SMARCA4 (BRG1) and SMARCA2 (BRM) are the two critical components of SWI/SNF ATPases that use ATP to generate energy for nucleosome remodeling, which is often mutated or silenced in cancer." (PMID 36844227, 2023). "SMARCA4 is related to several immune cells and genes in various forms of cancer." (PMID 37217462, 2023). "When grouping cancer genes into canonical cancer pathways, mutations in the SWI–SNF complex (for example, SMARCA4, ARID1B and SMARCB1) and certain members of the NOTCH signalling pathway (for example, EP300 and NCOR1) were under significant subclonal, but not truncal, selection in LUAD." (PMID 37046096, 2023). "Further, there is frequently reactivity with CK5/6, p63, and p40 in SMARCB1-deficient carcinoma, while these markers are generally negative in SMARCA4-deficient carcinomas." (PMID 36941503, 2023). "Lack of additional gene mutations in 170 commonly cancer-related genes in the current case argues for SMARCA4 loss being the major driver of transformation." (PMID 34389899, 2022). "The SWI/SNF genes, ARID1A, ARID1B, ARID2, SMARCA4, SMARCB1, and PBRM1 were mutated in up to 21.8% of all the cancers, and SWI/SNF mutation carriers had significantly higher TMB values as well as higher TMB-H and MSI-H proportions than their SWI/SNF-non-mutant counterparts in several malignancies." (PMID 36371186, 2022). "The mammalian SWItch/Sucrose Non-Fermentable (SWI/SNF) helicase SMARCA4 is frequently mutated in cancer and inactivation results in a cellular dependence on its paralog, SMARCA2, thus making SMARCA2 an attractive synthetic lethal target." (PMID 36357397, 2022). "SMARCA4 is a key member of the SWI/SNF ATPase‐dependent chromatin remodelling complex, but the details of the relationship between SMARCA4 deficiency and cancer development remain unclear." (PMID 35822082, 2022). "Thus, the inhibition of EZH2 using tazemetostat or GSK126 causes synthetic lethality in ARID1A-, SMARCA4-, SMARCB1-, PBRM1-deficient cancers." (PMID 36371186, 2022). "For example, SMARCA4 (BRG1) and SMARCA2 (BRM) are commonly mutated subunits in cancers." (PMID 35509102, 2022). "In this work we highlight the vulnerability of KDM6 inhibitors as a characteristic that could be exploited for treating SMARCA4-mutant cancer patients." (PMID 34262032, 2021). "On the other hand, the oncogenic role of SMARCA4 has been reported in several cancer types." (PMID 34675941, 2021). "The differentially expressed proteins were identified in the signaling pathways of granzyme B, sirtuins, eIF2, actin cytoskeleton, eNOS, acute phase response and calcium and were connected to the upstream regulators MYC, PI3K SMARCA4 and cancer-related chemical drugs." (PMID 33656060, 2021). "Furthermore, we observed a significant positive correlation between ITPR3 and SMARCA2 in these ovarian (n = 11, r = 0.825) and lung (n = 48, r = 0.584) cancer cell lines with low SMARCA4 expression." (PMID 34518526, 2021). "Together, these transcriptome analyses in SCCOHT cell lines indicate that Ca2+ homeostasis may be a commonly altered cellular process by SMARCA4, contributing to their roles in apoptosis regulation and cancer cell survival." (PMID 34518526, 2021). "The correlation of SMARCA4 with MSI in various cancer types was also investigated in our study." (PMID 34675941, 2021). "SMARCA4 expression is negatively correlated with ESTIMATEScore in most cancer types." (PMID 34675941, 2021). "Therefore, the pan-cancer analysis of SMARCA4 is vital and useful for comparing the similarities and differences among different cancers." (PMID 34675941, 2021). "The involvement of SWI/SNF in DDR supports the use of these genotoxic agents for treating cancers with SMARCA4/2 deficiency, which does not often co-occur with other druggable oncogenic mutations." (PMID 34518526, 2021).
cancer (continued). "Of note, A549 is also a SMARCA4-deficient NSCLC cell line and this independent study does further support the notion of elevating IP3R3 expression to enhance chemotherapy response in SMARCA4/2-deficient cancers." (PMID 34518526, 2021). "The lack of efficacy of SMARCA2/4 BRD inhibitors in SMARCA4-mutated cancers suggested the ATPase domain rather than the BRD as the therapeutically relevant target in oncology, which was confirmed by genetic complementation studies." (PMID 33941852, 2021). "TMB, MSI, MMR, and DNA methylation correlated with SMARCA4 dysregulation in cancers." (PMID 34675941, 2021). "Similarly to our study, larger and more general effects in chromatin accessibility than those in gene expression were demonstrated by SMARCA4 in other cancer cell models." (PMID 34127815, 2021). "We first examined the expression of SMARCA4 in the TCGA prostate normal and cancer cohort." (PMID 33596994, 2021). "In contrast to other cancer types where experimental SMARCA2 inhibition is synthetic lethal with SMARCA4 loss, SMARCA2 silencing may cooperate with SMARCA4 loss in SMARCA4/2-deficient SCCOHT and NSCLC for cancer development." (PMID 34518526, 2021). "High expression levels of SMARCA4 were observed in most cancer types." (PMID 34675941, 2021). "Algorithms of TIMER, CIBERSORT, CIBERSORT-ABS, QUANTISEQ, XCELL, MCPCOUNTER, and EPIC were further used to investigate the potential relationship between the infiltration level of different immune cells and SMARCA4 gene expression in diverse cancer types of TCGA." (PMID 34675941, 2021). "Association between SMARCA4 expression and TMB varies markedly among cancer types." (PMID 34675941, 2021). "However, some recent reports have demonstrated that SMARCA4 plays an important role in cell survival and proliferation in some types of cancer." (PMID 33987081, 2021). "The role of SMARCA4 across cancers and whether it can serve as a prognostic biomarker remain to be determined." (PMID 34675941, 2021). "Indeed, previous studies have shown that experimental inhibition of SMARCA4 in SMARCA4-proficient cancer cells enhanced response to DNA damaging agents." (PMID 34518526, 2021). "Finally, on a genetic basis, SNUCs can be divided into: NUT (midline) carcinoma, SMARB1-deficient carcinoma, SMARCA4-deficient carcinoma and IDH-mutant carcinoma." (PMID 34287240, 2021). "SMARCA4 has an antagonistic relationship with histone methyltransferase EZH2 (part of the PRC2 complex), which indeed is essential for survival and growth of SMARCA4-deficient cancer cells." (PMID 31996670, 2020). "Indeed, it has been suggested that SMARCA4 directly up‐regulates enzymes responsible for fatty acid (FA) and lipid biosynthesis, which can be utilized by cancer cells to provide energy for proliferation." (PMID 32162380, 2020). "Immunoprecipitation studies showed that cancer-associated mutations to the SMARCA4 ATPase domain do not prevent its incorporation into the BAF complex." (PMID 32629987, 2020). "Further in vitro studies demonstrated that targeting the ATPase activity of SMARCA2 and SMARCA4 might be a more potent target in cancer." (PMID 31769422, 2019). "Reciprocal to the known dependency of SMARCA4-deficient cancer cell lines on SMARCA225–27, the majority of SMARCA4-dependent ESCC cell lines (KYSE-270, KYSE-30, KSYE-510 and COLO-680N) displayed low or non-detectable levels of SMARCA2 mRNA and protein expression." (PMID 31406271, 2019). "In human cancer also concomitant loss of SMARCA2 and SMARCA4 expression has been described." (PMID 31406271, 2019). "Moreover, in clinical specimens, SMARCA4 expression is decreased in IPMN but is increased in the carcinoma." (PMID 31238554, 2019). "With the exception of the SMARCA4 that was found to be mutated twice at two different intronic positions (both predicted to have no functional impact), no other cancer-related gene was found to be recurrently mutated in the G1 group." (PMID 29915258, 2018).
cancer (continued). "While a high expression of SMARCA4 is associated with aggressive tumors, a high expression of SMARCA2 is associated with benign differentiated tumors, suggesting that SMARCA4 and SMARCA2 play opposite roles in cancer." (PMID 29391527, 2018). "Therefore, it is possible that SMARCA4 plays an essential role in the maintenance of cancer stem cells." (PMID 29391527, 2018). "What is the mechanism by which increased levels of SMARCA4 are important for cancer development?" (PMID 29391527, 2018). "Loss of SMARCA4 is necessary for this hypersensitivity, but as re-expressing SMARCA4 in a cancer cell line lacking it only partially rescued cells from AURKA knockdown, SMARCA4 loss is not sufficient for this sensitivity." (PMID 28102363, 2017). "Some SMARCA4-mutant cancer cells may be sensitive to inhibition of the second SWI/SNF catalytic subunit." (PMID 28594900, 2017). "Since not all mutation carriers have been diagnosed with cancer, the penetrance of the SMARCA4 gene appears incomplete." (PMID 25886974, 2015). "Therefore, this study examined the potential for expansion and adaptation of simultaneous CBP/p300 inhibitors for use against cancers with SS18–SSX fusion and the majority of SMARCA4/SMARCA2-deficient in addition to SMARCB1 deficient, which was reported previously." (PMID 39625239, 2025). "Thus, SMARCA4 has different roles in different cancer types." (PMID 39697230, 2024). "Indeed, SMARCA4 overexpression in cancer can serve as a prognostic indicator." (PMID 39697230, 2024). "However, for cancer patients with malignant tumors with SMARCA4 alterations, more downstream targets need to be demonstrated, which have been used in conjunction with their clinical coadministration, an approach that has a more long-term therapeutic outlook for the treatment of cancer." (PMID 39697230, 2024). "We hypothesized that this chemotherapy regimen might not be suitable for all SMARCA4-deficient carcinoma in head and neck; this has been confirmed in previous research." (PMID 38989233, 2024). "Despite these encouraging findings, the clinical activities of these inhibitors remain unknown as they mostly suppress proliferation and may not completely eradicate SMARCA4/2-deficient cancer cells." (PMID 37210563, 2023). "Furthermore, suppression of SCL38A2 also induced apoptosis and suppressed OXPHOS in SMARCA4/2-deficient cancer cells but not in controls, phenocopying glutamine deprivation." (PMID 37210563, 2023). "While additional cell context-specific alterations induced by SMARCA4/2-loss may also contribute to the metabolic reprograming, our results support the pivotal role of GLUT1/SLC38A2 underlying the glutamine and OXPHOS dependency of these cancer cells." (PMID 37210563, 2023). "Similarly, the fact that SMARCD3 is elevated from PanIN to PDAC suggests that it may be required to support ductal fate later in disease progression, and serve as an important enabler of SMARCA4 function in cancer." (PMID 36653361, 2023). "Given that either loss-of-function point mutations or inactivation of SMARCA4 have been outlined in several hematological malignancies, targeting its paralog (SMARCA2) might be a potential therapeutic alternative for the treatment of these cancers." (PMID 36810086, 2023). "SMARCA4-deficient carcinoma is composed of large, epithelioid cells lacking overt differentiation." (PMID 36941503, 2023). "Similarly SMARCA4-mutant cancers are vulnerable to SMARCA2 inhibition." (PMID 36361605, 2022). "For example, the BAF chromatin-remodeling complexes, which include BRG1 (SMARCA4) and BAF250a (ARID1A) that regulate transcription through the control of chromatin structure and the placement of polycomb repressive complex 2 (PRC2) across the genome are mutated in different cancer types." (PMID 35327559, 2022).
cancer (continued). "Immunohistochemically, SMARCA4 carcinomas lack any expression of markers of squamous differentiation, but may show expression of neuroendocrine markers, thus showing a significant phenotypic overlap with neuroendocrine carcinomas, that represent the main differential diagnosis." (PMID 35326613, 2022). "While sharing same genetic defect, convincing evidence is still lacking that SMARCA4-deficient carcinoma and SMARCA4-deficient teratocracinosarcoma might belong to the spectrum of same entity." (PMID 35307773, 2022). "Interestingly, SMARCA4 (SWI/SNF-related, matrix-associated, actin-dependent regulator of chromatin, Subfamily A, Member 4), the gene encoding BRG1, has been observed in both down- and up-regulated states in cancer, indicative of the diverse and complex BRG1 functions." (PMID 33596994, 2021). "Together, these observations show that reduced SMARCA4/2 expression correlates with resistance to different chemotherapies, including cisplatin, and suggest that SMARCA4 may play a dominant role in regulating drug responses in cancer cells." (PMID 34518526, 2021). "In SMARCA4 over expressing cancers, no significant recurrent mutations have been reported." (PMID 33596994, 2021). "Thus, SMARCA4 can be an oncogene for some cancers or in other contexts." (PMID 33853662, 2021). "Furthermore, no patients with SMARCA4-deficient cancers have been reported to show a CSS phenotype, and no CSS patients have been found to develop RTs." (PMID 27866340, 2017). "However, other authors describing SMARCA4 mutations in different cancers did not evaluate LOH as well (Shain & Pollack)." (PMID 25886974, 2015). "Although other core members of the SWI/SNF complex had been linked to cancer previously (SMARCB1 and SMARCA4 are known to have lost expression in a variety of tumors), this study showed that noncanonical members of the SWI/SNF complex could also play important roles in tumorigenesis." (PMID 25676695, 2015). "The aberrations of SMARCB1, SMARCA4, ARID1A, PBRM1, and SS18 within the SWI/SNF complex are frequently found in rare cancers and refractory cancers." (PMID 39625239, 2025). "Evidence in the literature points to a role for SMARCA4 and the SWI/SNF complex in modulating immune responses in cancer." (PMID 39813356, 2025). "Analysis of The Cancer Genome Atlas (TCGA) revealed a positive correlation between SMARCA4 and ZDHHC12 expression levels across multiple cancer types, including HCC." (PMID 40787880, 2025). "Constituent genes (e.g., SMARCB1, SMARCA4, SMARCA2, and SS18) of the SWI/SNF complex often harbor genetic abnormalities in various cancers." (PMID 39625239, 2025). "In both the control as well as in cancer patients it was found a positive correlation between KRAS and SMARCA4 (p = 0, R = 0.95 and p = 0, R = 0.84 respectively)." (PMID 38446332, 2024). "Moreover, designing prospective clinical SMARCA4-mutated or SMARCA4/KRAS-co-mutated NSCLC trials to evaluate targeted therapies and immunotherapy may lead to a better understanding of how to improve cancer patients’ outcomes and survival rates." (PMID 39063938, 2024). "LOF of the components of the SWI/SNF complex, mainly ARID1A, SMARCA4, or SMARCB1, has been demonstrated to sensitize cancer cells to PRC2 inhibitors." (PMID 39500892, 2024). "Researches indicated that insufficient SMARCA2 and/or SMARCA4, the ATPase activity subunits of SWI/SNF complexes, sensitized the cancer cells to chemotherapy or radiotherapy." (PMID 39627201, 2024). "Family VIII inhibitors that are selective for PBRM1 bromodomains over those of SMARCA4 and SMARCA2 have also been developed and studied for anti-cancer effects." (PMID 38390898, 2024). "ACBI1 effectively induced the swift, specific, and total degradation of SMARCA2, SMARCA4, and PBRM1 targets within MV-4-11 cancer cells." (PMID 38389844, 2024).